RNVU1-27 (RNA, variant U1 small nuclear 27)
Gene: Small nuclear RNA gene on chromosome 1 (148,522,601 to 148,522,765, forward strand). Ensembl gene ENSG00000274210.
Gene Ontology:
Molecular function: pre-mRNA 5'-splice site binding
Biological process: mRNA 5'-splice site recognition
Cellular component: U1 snRNP
Homologues: Paralogues in human: RNU1-1 (92% identical), RNU1-2 (92% identical), RNU1-27P (92% identical), RNU1-28P (92% identical), RNU1-3 (92% identical), RNU1-4 (92% identical), RNVU1-18 (92% identical), RNVU1-29 (92% identical), U1 (92% identical), RNVU1-28 (91% identical), RNVU1-7 (91% identical), RNU1-89P (90% identical), and 134 more.